ACE (angiotensin I converting enzyme)
Diseases named in the same sentence as ACE in open-access papers (continued):
Sharing a sentence is not in itself a finding about the gene and the disease.
coronary artery disease (316 papers, 2004 to 2025). "The ACE D allele is associated with the risk of coronary heart disease and myocardial infarction, which is also confirmed by meta-analysis data." (PMID 38707445, 2024). "Smoking, on the other hand, causes the release of reactive oxygen species by activating ACE, with a concomitant increase in lipid peroxidation, and reducing the antioxidant deface system which increases the risk of coronary heart disease to a large extent." (PMID 36110446, 2022). "There was weak evidence for an association of genetically proxied ACE inhibition with lower risk of stroke (OR 0.94, 95% CI 0.88 to 1.01; P = 0.06) and coronary artery disease (OR 0.95, 95% CI 0.89 to 1.02; P = 0.16)." (PMID 35113855, 2022). "Previous studies addressing the association between FH and ACE gene polymorphism focused on the potential risk of CHD coronary heart disease associated with ACE gene polymorphism in FH patients." (PMID 24289455, 2013). "In a meta-analysis including 43,733 coronary artery disease cases and 82,606 controls, the ACE D allele was associated with higher risk of coronary artery disease (OR[95%CI]=1.25 [1.16-1.35])." (PMID 23049672, 2011). "We have previously shown that D/D polymorphism of the ACE gene was significantly different between subjects with coronary artery disease and controls (p = 0.002) in Turkish population." (PMID 21955693, 2011). "As expected, patients with documented coronary artery disease had a significantly higher number of risk factors, were significantly older, and more frequently were treated with statins, platelet inhibitors, and ACE inhibitors/AT-1 receptor blockers." (PMID 21072182, 2010). "The role of angiotensin-converting enzyme (ACE) gene insertion/deletion (I/D) polymorphism in modifying the response to treatment modalities in coronary artery disease is controversial." (PMID 19497121, 2009). "PubMed was searched and a database of 58 studies with detailed information regarding ACE I/D polymorphism and response to treatment in coronary artery disease was created." (PMID 19497121, 2009). "This study aims to investigate whether the insertion/deletion (I/D) variant of ACE gene impacts cardiometabolic risk factors, premature coronary artery disease (PCAD), and severity of coronary lesions." (PMID 38849492, 2024). "The detection of ACE polymorphism in the leukocytes of patients suffering from coronary artery disease provided evidence that ACE genotype polymorphism may be associated with the development of atherosclerotic plaques." (PMID 38279313, 2024). "ACE I/D polymorphism is one of the genetic factors that may affect the severity of coronary artery disease." (PMID 37206099, 2023). "On the other hand, a polymorphism in the angiotensin-converting enzyme (ACE) gene characterized by insertion (I) or deletion (D) within its intron 16 has been described, with the D allele being associated with higher ACE levels and possible increased risk of coronary artery disease." (PMID 33228791, 2020). "Indeed, the INVEST trial found that among patients using ACE inhibitors in combination with CCBs with a history of coronary heart disease and class I obesity had a 48% lower risk of CV-related mortality, compared to normal weight patients." (PMID 30364090, 2018). "CAD =coronary artery disease; RF = risk factor; ACE = angiotensin convertingenzyme; IPAQ = International Physical Activity Questionnaire; HDL =high-density lipoprotein; LDL = low-density lipoprotein; VO2 = oxygenconsumption; HR = heart rate; bpm = beats per minute; W = watts." (PMID 26647745, 2015). "For the first time we demonstrate that nighttime noise substantially reduces FMD in patients with -or at risk for- coronary artery disease despite optimal, guideline conform concomitant cardiovascular medication including ACE-Inhibitors, AT-1 receptor blocker, statins and antiplatelet agents." (PMID 25145323, 2015).
coronary artery disease (continued). "Furthermore, estrogen decreases angiotensin converting enzyme (ACE) activity and the risk of coronary artery disease in women." (PMID 23308166, 2013). "In patients with coronary artery disease, treatment with ACE-inhibitor ramipril was associated with increase in both peripheral cell count, and functional activity of EPCs, the latter being assessed by proliferation, migration, adhesion and formation of vascular structures in vitro." (PMID 22474422, 2012). "Previous studies showed that the I/D polymorphism of ACE is highly related to the coronary artery disease (CAD), the DD genetic type is the independent risk factor of CAD." (PMID 28352370, 2010). "Even after adjusting for potential confounders, such as coronary artery disease (HR 1.24, p = 0.310) and medication use (ACE inhibitors/ARBs and Beta-blockers), baseline hs-cTnI and NT-proBNP levels remained non-significant predictors of AHREs." (PMID 41465789, 2025). "The angiotensin-converting enzyme (ACE) gene D polymorphism, which is associated with increased angiotensin levels, is also associated with ischemic heart disease and has been found to be associated with CCC severity in a Brazilian study." (PMID 40297326, 2025). "ACE inhibitors are applied extensively in the management of patients with hypertension, (chronic) heart failure, and coronary disease, whereas statins are used for primary and secondary prevention of cardiovascular events by lowering LDL cholesterol levels." (PMID 36194352, 2024). "Studies analyzing the expression of ACE in samples of coronary vessels obtained from patients suffering from coronary disease revealed the presence of ACE in the atherosclerotic plaques." (PMID 38279313, 2024). "Atorvastatin is used in the primary and secondary prevention of coronary heart disease, Valsartan and enalapril are angiotensin receptor blockers and angiotensin‐converting enzyme (ACE) inhibitors, respectively." (PMID 38974330, 2024). "For patients with comorbidities the Guidelines of the American College of Cardiology often recommend initiation of treatment with ACE inhibitors, e.g., for patients with stable ischemic heart disease or patients with preserved ejection fraction." (PMID 36991144, 2023). "ACE inhibitors improve CFR in womenwithout angiographic coronary artery disease and a low CFR at baseline." (PMID 39076281, 2023). "In hypertensive human patients, ESM-1 concentration correlates with the presence and severity of coronary artery disease, and the clinical benefits of ACE inhibitors include lower blood pressure and prevention of cardiovascular disease." (PMID 35790968, 2022). "Patients with coronary artery disease were under statin therapy, antiplatelets, ACE inhibitors and b-blockers." (PMID 34574014, 2021). "The two most common PPOs in the control group were the omission of vitamin D supplements among patients with a history of falls and the omission of ACE inhibitor in patients with documented coronary artery disease (CAD)." (PMID 32695426, 2020). "In the EUROASPIRE III study, conducted from 2006 to 2007, 94.2% of patients with coronary heart disease were treated with antiplatelet drugs, 90.1% with lipid-lowering drugs, 81.6% with beta-blockers and 71.5% with ACE-Is or ARBs." (PMID 29891821, 2018). "Six genes (ABCB1, PLAT, ACE, GH1, PECAM1, and RGS9) known to predispose people to coronary artery disease occur in the cn-LOH regions identified." (PMID 28120895, 2017). "In patients with coronary artery disease, overexpression of tissue ACE disrupts the angiotensin II/bradykinin balance, resulting in endothelial dysfunction." (PMID 27420103, 2016). "The effect of ACE inhibitors on pulsatile hemodynamics in patients with stable coronary artery disease was evaluated in the PEACE (Prevention of Events with Angiotensin-Converting Enzyme Inhibition) substudy." (PMID 25170513, 2014).
coronary artery disease (continued). "Angiotensin-converting enzyme (ACE) inhibition mitigates ROS formation and increases nitric oxide (NO) bioavailability in patients with coronary artery disease." (PMID 24264044, 2013). "60.5% of the patients in the statin group took ACE inhibitors, because the clinical impact of ACE inhibitor therapy for patients with coronary heart disease is already approved." (PMID 22533985, 2012). "Large clinical trials provided evidence of a lower incidence of ischemic heart disease when patients were treated with ACE inhibitors or AT1-receptor blockers compared to other antihypertensive drugs independent of blood pressure control." (PMID 21190563, 2010). "Earlier scientific investigations proved that ACE and MMPs are closely related to coronary diseases and the ACE inhibitors not only target ACE but also MMPs." (PMID 21197102, 2010). "The expression of angiotensin-converting enzyme (ACE) and chymase in calcified valves is mediated by macrophages and mast cells and is linked to low-density lipoprotein (LDL) cholesterol, echoing similar pathways in coronary artery disease." (PMID 40943088, 2025). "Furthermore, increased ACE expression in macrophages and smooth muscle cells within coronary artery plaques is recognized as a significant factor in the pathogenesis of ischemic heart disease." (PMID 41272596, 2025). "In another study, the relative risk of the D allele was estimated 1.07 for ischemic heart disease and 1.05 for MI, so the ACE genotype does not significantly increase the risk of ischemic heart disease and MI." (PMID 37193968, 2023). "Likewise, serum ACE concentration in vascular and coronary artery diseases has been documented to be more elevated in the D/D genotype than in its I/I counterpart, and this concentration heightens the risk of mortality in coronary artery disease." (PMID 36505135, 2022). "However, the efficacies of different ACE inhibitors in improving the migratory capabilities of ECPs in coronary artery disease (CAD) patients is unclear." (PMID 34707860, 2021). "Here, we aimed to investigate the role of B cells in athero-prone mice infused with AngII, which mimics some clinical situations in patients with coronary artery disease who may display increased ACE activity." (PMID 28646220, 2017). "For example, in a meta-analysis of 46 studies, Staessen and coworkers report that although the ACE D allele clearly increased risk of coronary heart disease and stroke, the effects on blood pressure were not significant." (PMID 27871254, 2016). "Comparison of angiographic severity of coronary artery disease indifferent ACE genotypes." (PMID 26735603, 2015). "Polymorphism of the Deletion/Insertion ACE gene is related strongly with ACE concentration in plasma and risk of coronary artery disease in diabetic and non-diabetic patients." (PMID 25340133, 2013). "Furthermore, long-term ACE inhibition improved forearm blood flow, a marker of improved vascular function, in patients with coronary artery disease and T2D in response to acetylcholine." (PMID 22013533, 2012). "Some of these gene polymorphisms, such as insertion/deletion (I/D) polymorphism of the ACE gene, and apolipoprotein E (APOE) have been reported as a disease-candidate risk for ICA stenosis and coronary artery disease." (PMID 20066125, 2009). "A particularly compelling study would be a head-to-head comparison of SGLT2is versus beta-blockers or ACE inhibitors in patients with stable ischemic heart disease, assessing whether SGLT2is could reduce angina burden, improve exercise tolerance, or lower the need for revascularization procedures." (PMID 40076724, 2025). "The observational Japanese Coronary Artery Disease study demonstrated the superiority of combined ACE inhibitor and statin therapy compared to monotherapy with either drug in patients with CAD." (PMID 36194352, 2024).
coronary artery disease (continued). "Our study is limited by small sample size and the fact that our patients have no documented coronary heart disease which may explain our inability to show an association between ACE gene polymorphism and FH." (PMID 24289455, 2013). "ACE and NOS3 are best known for their role in blood pressure regulation, but both are associated with 28 different diseases, including Alzheimer Disease, unstable angina, brain ischemia, coronary disease, systemic lupus erythematosus, preeclampsia, and autosomal dominant polycystic kidney disease." (PMID 19208189, 2009). "The combined use of antiplatelets, statins and ACE inhibitors was identified in only 34% of the patients in the REACT registry and in the coronary disease subgroup, approximately 40%10,20." (PMID 38378735, 2024). "Due to the fact that patients in the HOPE and EUROPA trials suspectedly had more advanced atherosclerosis, it is possible that the role in improving the prognosis of ACE inhibitor might be less important in patients at lower cardiovascular risk and without overt coronary heart disease." (PMID 34206708, 2021). "A significant effect of gene-gene interaction in coronary artery disease was detected for G-217A and M235T of AGT gene and I/D of ACE gene." (PMID 25961019, 2015). "The interactions between T174M, M235T, G-6A, A-20C, G-152A, G-217A of AGT gene, I/D of ACE gene, and A1166C of AT1R gene have been examined in coronary artery disease." (PMID 25961019, 2015). "Uptake rates of statins and angiotensin-converting enzyme inhibitors (ACE inhibitors) or angiotensin receptor blockers (ARB) more than doubled for secondary prevention and the management of stable coronary artery disease." (PMID 22719232, 2012). "Inaddition, we did not collect the individual medications (such as ACE inhibitor,beta blocker, etc.)for coronary artery disease." (PMID 40475712, 2025). "In a post hoc subgroup analysis of the GREACE (Greek Atorvastatin and Coronary Heart Disease Evaluation) study, the combined treatment effects of statins and ACE inhibitors compared to both drugs alone or neither drug were studied in 1600 patients." (PMID 36194352, 2024). "An angiotensin-converting enzyme (ACE) inhibitor was also absent for 422 patients who had systolic heart failure and/or documented coronary artery disease (N = 618; 68% 95% CI 65–72) (Supplementary START version 2 Table)." (PMID 38256457, 2024). "A WHO study in low- and middle-income countries found that only 70.6% of patients with cerebrovascular disease and 81.2% of patients with ischemic heart disease (IHD) were prescribed aspirin, while only 37.8% and 39.8% were prescribed angiotensin-converting enzyme (ACE) inhibitors, respectively." (PMID 36843692, 2023). "With the progressive implementation of guidance-supported treatments for coronary heart disease, such as percutaneous coronary intervention (PCI), antiplatelet therapy, statins, and angiotensin converting enzyme (ACE) inhibitors, the overall prognosis for CHD has improved significantly over time." (PMID 38274313, 2023). "First, according to the inclusion and exclusion criteria, the participants in this study had stable coronary artery disease with normal or slightly impaired left ventricular function and did not benefit from ACE inhibitors for conclusive evidence." (PMID 35313858, 2022). "Use of drugs such as statins, beta-blockers, or ACE inhibitors has been shown to reduce MPO levels in patients with acute coronary syndrome but not in patients with stable coronary artery disease." (PMID 26648662, 2015). "Among the patients with coronary heart disease, 18.8% did not receive aspirin, 51.9% did not receive a beta-blocker, 60.2% did not receive an angiotensin-converting enzyme (ACE) inhibitor and 79.2% did not receive a statin." (PMID 20534118, 2010).
coronary artery disease (continued). "In cases where angina due to non-obstructive coronary artery disease and ischaemia with no obstructive coronary artery disease results from endothelial dysfunction, ACE inhibitors are also recommended due to their anti-apoptotic effects on the endothelium of coronary arteries." (PMID 40004691, 2025). "Indeed, it was shown that ACE inhibition attenuated the superoxide-generating effects of angiotensin II, impaired the breakdown of bradykinin, and increased the production of EDNO in patients with coronary artery disease." (PMID 22013533, 2012). "There is evidence to suggest that statin/ACE inhibitor combination therapy maybe superior to ACE inhibitors alone for improving microcirculatory function andsymptom alleviation in patients with non-obstructive coronary artery disease." (PMID 39076281, 2023).